PLD1 (phospholipase D1)
Diseases named in the same sentence as PLD1 in open-access papers (continued):
Sharing a sentence is not in itself a finding about the gene and the disease.
PLD1 also shares sentences with these, for which no sentence is quoted: colorectal neoplasm (2 papers); congenital heart defects (2); COVID-19 (2); Hirschsprung disease (2); Hodgkins lymphoma (2); liver cancer (2); liver fibrosis (2); Non-alcoholic Fatty Liver Disease (2); bacterial infection (1); benign prostate hyperplasia (1); bladder cancer (1); brain injury (1); cerebral edema (1); cognitive (1); colon adenocarcinoma (1); diffuse large B-cell lymphoma (1); Ewing sarcoma (1); Glucose intolerance (1); hyperlipidemia (1); infectious disease (1); inflammation (1); inflammatory bowel disease (1); ischemia (1); kidney cancer (1); liposarcoma (1); medulloblastoma (1); metabolic disorders (1); Miscarriage (1); myeloma (1); Neurodegeneration (1).
A further 8 diseases each share a sentence with PLD1 in 1 paper.